CNTNAP2 (contactin associated protein 2)
Diseases named in the same sentence as CNTNAP2 in open-access papers (continued):
Sharing a sentence is not in itself a finding about the gene and the disease.
Intellectual disability (40 papers, 2011 to 2025). "Variants in genes such as BRAF and CNTNAP2 were associated with severe protein destabilization and phenotypic abnormalities, including encephalopathies and intellectual disabilities." (PMID 40282380, 2025). "Patients carrying the c.3709DelG mutation in CNTNAP2 were reported to have increased head circumference, epileptic seizures, language regression, intellectual disability, and ASD10." (PMID 34471112, 2021). "FOXP2 is known to regulate CNTNAP2 expression by binding to a regulatory sequence in its first intron, and CNTNAP2 dysfunctions have been implicated in specific language impairments, intellectual disabilities, and ASDs." (PMID 29345619, 2018). "We report on patients with heterozygous defects in CNTNAP2 or NRXN1 associated with severe intellectual disability, which has only been reported for recessive defects before." (PMID 21827697, 2011). "Expanding the observations from previous studies we now found that heterozygous defects in CNTNAP2 or NRXN1 can also be seen in association with severe intellectual disability." (PMID 21827697, 2011). "In 8 further patients with variable intellectual disability and heterozygous deletions in either CNTNAP2 or NRXN1, the remaining allele was sequenced." (PMID 21827697, 2011). "Considering the association between CNTNAP2 and intellectual disabilities, one might infer that rs2710102 itself is related to intelligence." (PMID 34898614, 2021). "In addition, mutations in contactin associated protein-like 2 gene (CNTNAP2), a member of the neurexin superfamily, are linked to childhood-onset epilepsy along with intellectual disabilities and autism." (PMID 32719346, 2020). "Thus it is difficult to define if the intellectual disability is associated with the CNTNAP2 mutation at all in these patients." (PMID 21827697, 2011). "To further delineate the clinical phenotype associated with potentially recessive defects in any of the two genes, we screened a group of patients with either severe intellectual disability resembling Pitt-Hopkins syndrome or the phenotypes caused by recessive CNTNAP2 or NRXN1 defects." (PMID 21827697, 2011). "Prior work has shown that mutations in the contactin associated protein-like 2 (Cntnap2) gene are associated with ASD, cortical dysplasia-focal epilepsy (CDFE), intellectual disabilities, and seizures in patients." (PMID 41408339, 2025). "Biallelic CNTNAP2 variants have been associated with Pitt‐Hopkins‐like syndrome (MIM: #610042), a disorder characterized by developmental delay, intellectual disability, speech impairment or regression, behavioral abnormalities, and seizures." (PMID 37805811, 2024). "Genetic defects to Contactin-associated protein-like 2 (CNTNAP2) can cause many neurological disabilities in humans, including ASD and intellectual disability." (PMID 36253443, 2023). "Here, we describe a novel pathogenic CNTNAP2 mutation in an 8-month-old infant who manifested spontaneous recurrent seizures (SRS) and intellectual disability." (PMID 34737720, 2021). "The majority of reported patients carry heterozygous disruptions of CNTNAP2 and usually display some combination of core phenotypes including intellectual disability (ID), seizures, autistic features and impaired language." (PMID 26843181, 2016). "All seven patients with heterozygous defects in CNTNAP2 in this study showed severe to profound intellectual disability." (PMID 21827697, 2011). "It is also noteworthy that EHMT targets include fly orthologs of NF1, FMR1, FMR2, CNTNAP2, GDI, DLG3, and of many more genes underlying syndromic and non-syndromic forms of intellectual disability." (PMID 21245904, 2011). "We found heterozygous defects in CNTNAP2 and NRXN1 in patients with severe intellectual disability, therefore expanding the clinical spectrum associated with monoallelic defects in either gene." (PMID 21827697, 2011).
Intellectual disability (continued). "Since many NDDs including ASD are characterized by a plethora of developmental deficits, intellectual disability, seizures and impaired social cognition, we selected Cntnap2 KO (Cntnap2−/−) mice to test our hypothesis." (PMID 39877097, 2025).
thymoma (29 papers, 2008 to 2026). A neoplasm arising from the epithelial cells of the thymus. "CNTNAP2 was highly up-regulated in MG-thymoma, exhibited low expression in colon compared to thymus, and was down–regulated in colon cancer." (PMID 18545673, 2008).
Autoimmunity (27 papers, 2015 to 2025). The occurrence of an immune reaction against the organism's own cells or tissues. "The most frequent and best characterized NSAS are anti-N-methyl-D-aspartate receptor (NMDAR) encephalitis, and autoimmunity with NSAbs targeting the leucine-rich, glioma-inactivated protein-1 (LGI1), and the contactin-associated protein-2 (CASPR2)." (PMID 35515348, 2022).
Ataxia (23 papers, 2012 to 2025). Ataxia refers to impaired coordination of voluntary muscle movement. "Further, individuals with CNTNAP2 mutations display cerebellar malformations and CNTNAP2 antibodies are associated with a mild form of cerebellar ataxia." (PMID 34593517, 2021). "Incidentally, CNTNAP2 antibodies have been identified in sera from patients with otherwise unexplained progressive cerebellar ataxia with mild to severe cerebellar atrophy, supporting the role of this gene in cerebellar development and function." (PMID 34593517, 2021).
dyslexia (22 papers, 2014 to 2023). A learning disorder characterized by an impairment in processing written words. "Recently, the contactin-associated protein-like 2 (CNTNAP2) gene has been found to have sex-specific links with dyslexia in a Chinese population." (PMID 30687153, 2018). "Moreover, recent genetic studies have also found evidence that the CNTNAP2 gene variant is associated with gender differences among dyslexia children in China." (PMID 33003545, 2020). "Interestingly,CNTNAP2 been has identified as a dyslexia susceptibility gene and several variants are associated with gender specific differences (Guet al., 2018)." (PMID 31448102, 2019). "Among the top 20 genes with the highest priority DRD2, DRD4, CNTNAP2 and GRIN2B are mentioned in the literature as directly linked with the comorbidity of ADHD and dyslexia." (PMID 37667328, 2023). "One child presented a duplication on chromosome 7q35 involving CNTNAP2, a gene candidate for dyslexia, DLD, ASD and CAS." (PMID 35207801, 2022). "Three CNVs were identified in genes that have been associated with dyslexia (CTNND2, NRCAM, and CNTNAP2) and their role in bone is currently unknown." (PMID 30042735, 2018). "For example, forkhead box P2 (FOXP2) and its downstream target gene contactin associated protein-like 2 (CNTNAP2) have been shown to be an important link in the networks of several speech and language disorders, including SLI, dyslexia, stuttering and dyspraxia." (PMID 25643770, 2015). "It has been hypothesized that shared endophenotypes in these disorders, particularly between ASD and ADHD, may be due to shared genetic factors; CNTNAP2, which is expressed in the cerebellum and potentially impacts language function, has been linked to both ASD and dyslexia." (PMID 24904314, 2014). "They found that there are overlapping expression patterns in human dyslexia-related genes (ROBO1 and KIAA0319, and CNTNAP2 and CMIP) and the expression patterns of these genes in the marmoset brain." (PMID 37760998, 2023).
cortical dysplasia-focal epilepsy syndrome (17 papers, 2015 to 2025). An autosomal recessive condition caused by mutation(s) in the CNTNAP2 gene, encoding contactin-associated protein-like 2. "Previous observations have shown cortical neuronal migration abnormalities in CNTNAP2−/− mice which is similar to aberrant cortical migration patterns observed in CDFE syndrome patients with the CNTNAP2 mutation." (PMID 37371370, 2023). "Biallelic CNTNAP2 loss has been associated with “Pitt-Hopkins-like syndrome-1” (MIM#610042), while the pathogenic role of heterozygous variants remains controversial." (PMID 37183190, 2023). "CNTNAP2 has been associated with cortical dysplasia-focal epilepsy syndrome (CDFES; OMIN#610042) or autosomal dominant epilepsy with auditory features." (PMID 31875159, 2019). "Recessive CNTNAP2 variants are associated with Pitt-Hopkins like syndrome 1 and cortical dysplasia-focal epilepsy syndrome (MIM #610042)." (PMID 30675382, 2019). "Cortical Dysplasia-focal Epilepsy (CDFE) syndrome is caused by mutations in Contactin Associated Protein 2 (CNTNAP2), where a subgroup of patients express autistic behavior." (PMID 28420080, 2017). "Recessive loss-of-function mutations in CNTNAP2 cause Pitt-Hopkins-like syndrome, symptoms of which include severe intellectual disability, lack of speech and seizures." (PMID 26273832, 2015). "Cntnap2 is a gene that is associated with both ASD and CDFE syndrome, and sleep problems are widely recognized in both patient populations." (PMID 41408339, 2025).
autoimmune disease (16 papers, 2015 to 2025). A disorder resulting from loss of function or tissue destruction of an organ or multiple organs, arising from humoral or cellular immune responses of the individual to their own tissue constituents. "Contactin-associated protein-like 2 Caspr2 (also known as CNTNAP2) is a CAM that belongs to the Neurexin family and is associated with both neuropsychiatric disorders and autoimmune diseases." (PMID 26217189, 2015). "Notably, CNTNAP2 encodes CASPR2 protein which is expressed in central nervous system (CNS) and peripheral nervous system (PNS) playing a role in neurodevelopmental disorders and in the autoimmune disease Sjogren’s syndrome (SS)." (PMID 33921415, 2021).
Cognitive impairment (16 papers, 2011 to 2025). Abnormal cognition is characterized by deficits in thinking, reasoning, or remembering. "To test the hypothesis that loss of experience-dependent PV IN plasticity in CA3/CA2 is a substrate for cognitive impairments and seizures in NDDs, we chose the Cntnap2 KO model of NDD risk." (PMID 39877097, 2025). "Given the association between CNTNAP2 and human cognitive disorders, and the evidence for its potential role in human evolution, this review aims to synthesize clinical, experimental, and evolutionary data to understand CNTNAP2 function and the biological consequences of its disruption." (PMID 36340692, 2022). "In turn, this human-specific increase in CNTNAP2 expression may have contributed to human brain function and increased human susceptibility to cognitive disorders." (PMID 36340692, 2022).
Anxiety (12 papers, 2016 to 2026). Intense feelings of nervousness, tension, or panic often arise in response to interpersonal stresses. "RESULTS: Treatment with 7-NI improved ASD-like behavioral deficits in Cntnap2 and Shank3 mutant mice, including increased sociability and reduced anxiety-like behavior." (PMID 42010670, 2026). "Cntnap2 KO mice have normal anxiety-related responses but show abnormal vocal communication, repetitive behaviors, and abnormal social interactions." (PMID 40642208, 2025). "For instance, unlike the genotype-independent increase in sensitization in adult Poly I:C MIA offspring, anxiety-like behavior was only increased in Wildtype but not Cntnap2-deficient MIA offspring." (PMID 36998729, 2023). "Although Cntnap2–/– animals have previously shown normal open field center time compared to controls, Poly I:C MIA is known to decrease center time in this paradigm, which is linked to increased anxiety." (PMID 36998729, 2023). "At a behavioral level, Cntnap2 KO mice were characterized by hyperactivity and deficits in hippocampal-dependent spatial object recognition in addition to the already established behavioral phenotypes such as repetitive behavior and altered levels of anxiety." (PMID 34758298, 2021). "Next, we tested the separate and combined effects of Cntnap2 genotype, Poly I:C MIA, sex age on the time spent in the center of the open field, a rodent measure of anxiety behavior." (PMID 36998729, 2023). "Several studies of monogenetic (Shank3, Cntnap2) or environmental (maternal HFD) ASD report no benefit of LR in reducing hyperactivity or anxiety in male or female offspring." (PMID 39520540, 2025). "By contrast, Cntnap2−/− mice were indistinguishable from C57 mice in measures of anxiety as previously reported using a different task." (PMID 37596047, 2023). "Notably, we also identified novel findings: CNTNAP2 knockout mice displayed increased rearing behavior and lacked anxiety-like behaviors, diverging from the assumption that anxiety is a common feature of this model." (PMID 40642208, 2025). "Notably, our study also identified novel results, including increased rearing behavior and a lack of anxiety in the CNTNAP2 knockout mice." (PMID 40642208, 2025).
attention deficit-hyperactivity disorder (12 papers, 2013 to 2025). A disorder characterized by a marked pattern of inattention and/or hyperactivity-impulsivity that is inconsistent with developmental level and clearly interferes with functioning in at least two settings (e.g. at home and at school). "Other disorders associated with CNTNAP2 include schizophrenia, attention deficit hyperactivity disorder (ADHD), Tourette syndrome, dyslexia, and major depression." (PMID 36340692, 2022). "CNTNAP2 has been reported to be an important genetic factor for differentiating the pathogenesis of language impairment in autism spectrum disorder (ASD) or attention-deficit hyperactivity disorder (ADHD)." (PMID 25941478, 2015). "In addition, haploinsufficiency for CNTNAP2, resulting from gene disruption, has been implicated in other clinically distinct behavioral disorders such as Gilles de la Tourette syndrome (GTS; MIM 137580), attention-deficit/hyperactivity disorder (ADHD) and, schizophrenia and epilepsy." (PMID 24147096, 2013).
glioma (11 papers, 2013 to 2025). A benign or malignant brain and spinal cord tumor that arises from glial cells (astrocytes, oligodendrocytes, ependymal cells). "CNTNAP2, another tumor suppressor, is recurrently mutated in glioma and melanoma as annotated in COSMIC." (PMID 41153425, 2025). "CNTNAP2 was reported to be an independent prognostic factor, with a high CNTNAP2 mRNA expression level associated with a good prognosis in glioma." (PMID 36975488, 2023). "CNTNAP2 (Contactin-associated protein-like 2), a member of the neurexin family, has been proposed as a tumor suppressor in glioma, and in our cohort, CNTNAP2 showed 74 NCCMs with 29 patients having one or more variants." (PMID 32513296, 2020). "CNTNAP2 is an important neurogenesis gene that some studies suggest is a tumor suppressor gene in glioma." (PMID 33917421, 2021). "The CNTNAP2 gene also functions as a cell adhesion molecule and has been found to be either methylated or deleted in several different cancer types, e.g. glioma, myleoid leukemia, and pancreatic adenocarcinoma." (PMID 24885002, 2014). "CNTNAP2 is known to be a tumor-suppressor gene for gliomas, and is disrupted by chromosomal translocations and gene mutations." (PMID 23544068, 2013).
cortical dysplasia (10 papers, 2010 to 2024). "In a recent study, three out of 20 patients with biallelic CNTNAP2 variants exhibited neuroimaging signal abnormalities consistent with focal cortical dysplasia (FCD) in the anterior temporal lobes." (PMID 37805811, 2024). "Out of 44 previously reported patients harboring pathogenic or likely pathogenic biallelic CNTNAP2 variants whose MRI findings were described, seven (7/44; 16%) exhibited similar cortical dysplasia‐like findings on neuroimaging." (PMID 37805811, 2024). "The homozygous CNTNAP2 frameshift variant, c.3709delG, identified in a consanguineous Old-Order Amish family, was the first reported mutation for cortical dysplasia-focal epilepsy syndrome." (PMID 35911904, 2022). "A recessive nonsense mutation in the contactin associated protein-like 2 (CNTNAP2) gene was shown to cause a syndromic form of ASD, cortical dysplasia and focal epilepsy syndrome (CDFE)." (PMID 27458336, 2016).
Tourette syndrome (10 papers, 2012 to 2025). A neurologic disorder caused by defective metabolism of the neurotransmitters in the brain. "A set of intronic deletions of CNTNAP2 gene has also been suggested to have a causative role in individuals with a wide phenotypic spectrum, including Pitt-Hopkins syndrome, cortical dysplasia–focal epilepsy syndrome, Tourette syndrome, language dysfunction, and abnormal behavioral manifestations." (PMID 33042910, 2020).
focal epilepsy (9 papers, 2010 to 2022). A seizure caused by a localized disorder. "The other APE with CNTNAP2 p.Arg1288Cys had non-lesional focal epilepsy without auditory aura." (PMID 31875159, 2019).
depression (8 papers, 2013 to 2022). "These genes include CHD7, ADCY3, ANK3, NWD1, CNTNAP2 and TSNAX-DISC1, each of which has been carefully considered and contrasted as no previous link between neural disorders or psychiatric conditions, including depression, has been made for risk preference." (PMID 34696705, 2022). "Additional examples include schizophrenia for RELN, GluR6, GRIN2A, GRIN2B, and CNTNAP2, childhood absence epilepsy for GABRB3, ADHD and depression for 5-HTT, and major depression for TPH2." (PMID 23935565, 2013).
bipolar disorder (7 papers, 2011 to 2020). A disorder of the brain that causes unusual shifts in mood, energy, activity levels and the ability to carry out day-to-day tasks. "Finally, in a CNV mircroarray study of an extended bipolar disorder family with 5 affected relatives we previously identified a 131kb deletion in CNTNAP2 intron 1, removing a FOXP2 transcription factor binding site." (PMID 30586385, 2018). "Furthermore, we report the deletion of one copy of CNTNAP2 in two patients with bipolar disorder and one unaffected relative from an extended family where five relatives were affected with this condition." (PMID 30586385, 2018). "We identified three rare deletions in KCNJ6, UNC13C, OTOL1 and 7 rare duplications in CNTNAP2/MIR548F3, CORO7/VASN, DTNB, EMID2, KCNF1, PDPR and SGTA/THOP1 that are present in children with bipolar disorder (and their parents)." (PMID 25887117, 2015).
language delay (7 papers, 2011 to 2021). "These included genes associated with behaviorally important substances such as glucocorticoids, GABA, septin, calcineurin, as well as the genes CNTNAP2 (implicated in language delay in autistic children) and FOXP2 (known to be involved in vertebrate communication)." (PMID 23049809, 2012). "Rare and common variants of CNTNAP2, the gene encoding Caspr2, have been linked to an increased risk of ASD or ASD-related phenotypes including language delay and developmental language disorders." (PMID 34721260, 2021).
language disorder (7 papers, 2010 to 2023). A category of disorders characterized by an impairment in the development of an individual's language capabilities, which is in contrast to his/her non-verbal intellect. "A new strong candidate gene for psychiatric and language disorders is contactin-associated protein-like 2 (CNTNAP2) gene (MIM#604569)." (PMID 33042910, 2020). "Mutations of FOXP2 and CNTNAP2 were linked to speech and language disorders and ASD." (PMID 23815876, 2013).